KRTAP19-3 (keratin associated protein 19-3)
Description:
In the hair cortex, hair keratin intermediate filaments are embedded in an interfilamentous matrix, consisting of hair keratin-associated proteins (KRTAP), which are essential for the formation of a rigid and resistant hair shaft through their extensive disulfide bond cross-linking with abundant cysteine residues of hair keratins. The matrix proteins include the high-sulfur and high-glycine-tyrosine keratins.
Synonyms: KAP19.3; GTRHP
Tractability: No criterion of Open Targets' tractability assessment is met for any kind of drug.
Gene: Protein-coding gene on chromosome 21 (30,491,462 to 30,492,013, reverse strand). Ensembl gene ENSG00000244025.
Pathways (Reactome):
Developmental Biology: Keratinization
Gene Ontology:
Molecular function: protein binding
Cellular component: cytosol
Genetic constraint (gnomAD): Loss-of-function variants: 1 observed, 1.25 expected, observed/expected ratio (o/e) 0.8, 90% interval 0.23 to 1.87. That is too few expected variants to judge how well the gene tolerates losing a copy. Missense variants: 106 observed, 106.11 expected, observed/expected ratio (o/e) 1, 90% interval 0.85 to 1.17. Synonymous variants: 37 observed, 43.46 expected, observed/expected ratio (o/e) 0.85, 90% interval 0.65 to 1.12.
Homologues: Orthologues: chimpanzee KRTAP19-3 (99% identical), pig KRTAP19-3 (57% identical).